IL6 (interleukin 6)
Diseases named in the same sentence as IL6 in open-access papers (continued):
Sharing a sentence is not in itself a finding about the gene and the disease.
infection (continued). "In addition to the cell migration, the infection of microglia with P. gingivalis significantly increased the mRNA expression of proinflammatory mediators, including IL-6, TNF-α, and iNOS, without affecting the mRNA expression of anti-inflammatory mediators, including IL-10, arginase-1 and IL-4." (PMID 28924232, 2017). "Bilophila wadsworthia infection resulted in the reduction of body weight and fat mass, apparent hepatosplenomegaly and elevated serum inflammatory factors, including serum amyloid A and interleukin-6, while without significant change of the overall gut microbiota structure." (PMID 29090023, 2017). "Additionally, PCV2 infection of PK-15 cells that were treated with SOCS3 siRNAs exhibited elevated levels of IL-6 and TNF-α, compared with control cells, thereby demonstrating that PCV2 activated SOCS3 to minimize these proinflammatory responses to promote a subclinical infection." (PMID 27581515, 2016). "We then determined whether IL‐6 signaling was required for pMacs to limit the ability of UPEC to exploit extra‐macrophagic free iron by treating pMacs in the presence or absence of iron supplementation during the infection course, with a control antibody or anti‐IL‐6Rα added during infection." (PMID 27980776, 2016). "Therefore, we demonstrated that immunobiotic administration induce an early increase in the levels of TNF and IL-6 in the respiratory tract after poly(I:C), RSV, or IFV challenge, while the levels of those proinflammatory factors are significantly reduced later during infection." (PMID 28066442, 2016). "Thus, inhibition of IL-6 production by F-4 would suggest an immuno-suppressive action, but its concomitant stimulatory effect on TNF-α, an important cytokine involved in the development of resistance to infection and cancer with roles in necrosis and apoptosis, suggests a more subtle mechanism." (PMID 27104574, 2016). "Furthermore, IL-6 and TNF-α gene induction was higher in mouse brains challenged with JEV-WT than JEV-NS5–M19A and IL-6 protein could be detected in the sera of mice with JEV-WT infection." (PMID 25816318, 2015). "Finally, it is interesting to note that STAT3-dependent cytokines, such as IL-6, IL-10, and IL-21, as well as MyD88-dependent IL-1 have been suggested to play a role in memory CD8+ T cell differentiation and functional maturation following immunization and infection." (PMID 24842874, 2014). "Indeed, IL-6 was not consistently detected following Schu S4 infection (data not shown)." (PMID 25295729, 2014). "The discrepancy in plasma IL-6 changes during HD may in part be explained by differences in patient characteristics as patients included in our study were well-nourished and showed no sign of infection or inflammation." (PMID 23557110, 2013). "Hence our study aimed to assess the value of simultaneous measurement of PCT and IL-6 along with the white blood cell, neutrophil and lymphocyte count, blood culture and high sensitive C- reactive protein (hs-CRP) in neonate populations with a rapid diagnosis of the infection." (PMID 22708043, 2012). "For the cytokines Rantes, GM-CSF, Eotaxin, IL-13, IL-9, IL-6 and IL-1b there was no significant mean difference in concentration among the first three time-points (15 min, 30 min and 60 min) and the last two time-points (4 hrs and 10 hrs) for both the H37Rv and Δ-mce1 H37Rv-infections." (PMID 22039457, 2011). "Interestingly, for TNF-αactivation was largely independent of productive infection, a finding that also indicates that induction of IL-6 and IL-10 are not being induced as a by-product of TNF-α up-regulation, but rather that these mediators are independently induced." (PMID 21572983, 2011). "Finally, they represented diverse molecular classes – cytokines (TNF, IL-12p40, IL-6, IL-10, GM-CSF), chemokines (RANTES, MCP-1), enzymes (iNOS, cyclooxygenase [COX] 2) and cell-surface co-stimulatory proteins (Delta-4, CD40, GITRL) – with known roles in immune responses to infection." (PMID 21170273, 2010).
infection (continued). "In addition to the evidence that peripherally immune-derived cytokines can trigger neuro-endocrine responses during infection and inflammation, several non-immune functions of cytokines such as TNFα, IL-1β and IL-6 synthesised within the CNS in the absence of disease have been described." (PMID 19254758, 2009). "Similarly, analysis of IL-6 at the transcriptional level by Northern blot showed induction of IL-6 mRNA in both cell clones infected with IBV at 8 (lanes 1 and 5), 12 (lanes 2 and 6), 16 (lanes 3 and 7) and 24 (lanes 4 and 8) hours post-infection, respectively." (PMID 18231581, 2008). "Moreover, our data suggest that changes detected early in the evolution of either acute-phase proteins or IL-6 may alert the surgeon to the development of insidious infection that may not have been clinically evident until then." (PMID 17505683, 2007). "The infection induces a specific cytokine response characterized by an increase in the secretion of IL-8 and tumor necrosis factor (TNF)-α, but not of IL-6." (PMID 42138646, 2026). "gonorrhoeae strain MS11mkC, we did not see similar increases in urine IL-6, TNF-α, or IL-1β, although differences in IL-6, TNF-α were observed in participants with later development of infection." (PMID 41810365, 2026). "IL-6 is also highly useful (AUC = 0.89), whereas CRP and PCT levels do not appear to be reliable for the early diagnosis of infection." (PMID 40806991, 2025). "Infection of THP-1 cells with F. novicida WT, wbtF mutant, and the complemented strain produced similar TNF-α and IL-6 responses, indicating that wbtF does not significantly affect cytokine production." (PMID 41141590, 2025). "Elevated IL-6 and C-reactive protein (CRP) levels were observed in the majority of cases, indicating a systemic inflammatory response even in the absence of overt infection." (PMID 41458669, 2025). "Limitations of our study include the absence of baseline pre-infection OCTs, unavailability of serum biomarkers (e.g., IL-6, TNF-α), and lack of a defined post-infection imaging window." (PMID 40790570, 2025). "This mouse model showed detectable viral SARS-CoV-2 RNA and significantly elevated levels of pro-inflammatory interleukins (e.g., IL-6) and tumor necrosis factor-alpha (TNF-a) in the lung tissues 4 days, but not 15 days, after infection." (PMID 41472298, 2025). "Despite high NPV (88%), TNF-α—like IL-6 (NPV = 82%) and IL-8 (NPV = 88%)—failed to differentiate infection severity (p > 0.05 for all)." (PMID 40647525, 2025). "Serum levels of IL-10, IL-2, IL-6, IL-8, and TNF-α were analyzed and compared between patients with and without HAdV-36 infection." (PMID 40284995, 2025). "In this context, the present study aims to compare IL-10, IL-2, IL-6, IL-8, and TNF-α levels between patients with and without HAdV-36 infection." (PMID 40284995, 2025). "Critically, our data provide clinical support for these mechanisms by demonstrating significant negative correlations between VA levels and both IL-6 and PCT, directly linking VA status to inflammation and infection severity in our cohort." (PMID 41311806, 2025). "SRT1720 reduced plasma IL-6 and TNF-α levels at 42 h after infection, while not affecting plasma IL-12 or IFN-γ." (PMID 41096578, 2025). "The distinct negative correlations of VA with IL-6 and PCT, and of VD with PCT, provide clinical support for the involvement of these vitamins in modulating infection and inflammatory responses in the elderly." (PMID 41311806, 2025). "Notably, administration of oxytocin has been shown to upregulate pro-inflammatory cytokines, including interleukin-6 and tumor necrosis factor-α, through activation of peripheral mononuclear cells, thereby contributing to maternal hyperthermia even in the absence of infection." (PMID 41040641, 2025).
infection (continued). "The aim of this study was to examine the relationship between IL-6 levels and length of ICU stay in patients with DKA without signs of infection and to investigate how this relationship is related to inflammatory markers NLR and CAR." (PMID 40005437, 2025). "Group C had low IL-6 expression and high APOA1 expression when not infected with the pathogen, and the two were inversely adjusted after infection in line with the results of the previous investigations." (PMID 40005807, 2025). "The absence of active infection preoperatively was supported by unremarkable CRP and interleukin-6 levels upon admission, as well as normal chest x-ray findings." (PMID 41395310, 2025). "In the absence of infection, treatments with BRP and 7-O-methylvestitol (both 64 μg/mL) increased IL-6 production compared to the untreated control and conventional treatment (**** p < 0.0001)." (PMID 40871442, 2025). "Enteritidis CMCC50041 infection increased the transcript levels of the intracellular cytokines IL-8 and TNF-α but not as well on those of IL-6 and INF-γ." (PMID 39927265, 2025). "This is evidenced by normal counts of blood cells and platelets, a lack of pro-inflammatory cell recruitment at the infection site, and minimal serum levels of cytokines such as IL-1β, TNF-α, IL-10, and IL-6." (PMID 40606156, 2025). "Later during infection, however, tlr4 mutant mice had elevated, albeit not significantly higher, amounts of TNF-α, IL-1α, and IL-6 relative to WT mice, consistent with persistent infection." (PMID 40817088, 2025). "Inflammation is characterized by an increase in pro-inflammatory cytokines interleukin 1 β (IL-1β), interleukin 6 (IL-6), and tumor necrosis factor-α (TNF-α), even in the absence of overt infection or injury." (PMID 40509402, 2025). "While not viewed as classical immune cells, upon infection or other injury, they orchestrate immune activation through the secretion of various pro-inflammatory cytokines (e.g., TNF-α and IL-6) and chemokines (e.g., MCP-1)." (PMID 40278266, 2025). "Taken together, these findings demonstrate that the co-culture of P. gingivalis and F. nucleatum, rather than the monocultures or the separate infections with the bacteria, increases the expressions of TNF-α, IL-1β, IL-6, and IL-8 in OKs." (PMID 38612423, 2024). "We also tested TNF, IL-1β and IL-6 in BALF under homeostasis and observed no significant changes, though they began to trend higher on day 10 post-infection in ECSparcl1-OE mice." (PMID 38762489, 2024). "Together these data show that IL-6 (but not CD4 cells) contributes to the initial awakening and expansion of dormant DCC, but that later during the infection following the recruitment of T cells, CD4 cells are required for the maintenance of the awakened DCC." (PMID 38645169, 2024). "Macrophages in older adults also exhibit an inflammatory phenotype, producing pro-inflammatory cytokines such as IL-6, TNF-α, and IL-1β even in the absence of infection." (PMID 39720706, 2024). "Post-infection vaccination did not affect plasma levels of TNF and IL-6, irrespective of the number of doses or PCC status." (PMID 38316833, 2024). "Our results are in agreement with previous findings showing an increase in serum IL-6, OSM, and LIF levels in BDL rats without any obvious signs of infection." (PMID 39391493, 2024). "Despite the lack of viral titer in the human astrocytes, the infection with H7N9 promoted an increased expression of pro-inflammatory cytokines, such as TNF-α, IL-6, IL-8, CCL2, and IFN-β 24 hpi." (PMID 39203555, 2024). "CRS should be considered in the absence of clear evidence of infection during a fever and the presence of CAR T‐cell expansion and elevated levels of IL‐6 and other cytokines." (PMID 38923216, 2024). "STING−/− PM presented decreased levels of IL-6 and TNF-α compared to WT PM after infection with C. perfringens, stimulated or not with HKCA." (PMID 38622656, 2024).
infection (continued). "In the H1N1 VACC group, productions of IL-6 and IFN-α after 272/20-H1avN1 infection were not evidenced in sera." (PMID 38773540, 2024). "Levels of IL-8, IL-6, and MCP-1 (CCL2) were not yet detectably higher in either infection or IL-17C treatment by 6h." (PMID 38704381, 2024). "The expression of Il6, Ifnb, Tnf, and Cxcl10 after HAZV infection was significantly increased in WT cells, and was not altered by UV-treated HAZV." (PMID 39348382, 2024). "Furthermore, SARS-CoV-2 D614G[Omicron spike] infection resulted in a significantly increased expression of ISGs Mx1, Oas1, and Viperin as well as Cxcl10, while pro-inflammatory mediators Cxcl1, Ccl2, and Il6 were not significantly altered in any group compared to the uninfected mice." (PMID 38742107, 2024). "Non-immunized animals displayed an increase in IFN-γ, TNF, IL-6 and IL-12 after inoculation with EHDV-8, with an important and significant increase at day 5 post-infection compared to the immunized group." (PMID 38904031, 2024). "We observed that M. pneumoniae infection in vitro induced comparable mRNA expression of Il-1β, Il-6, and Tnf-α in WT neutrophils and Irg1 KO neutrophils compared to controls after 12h, suggesting that itaconate may not impact neutrophils expressing these cytokines during infection." (PMID 39499730, 2024). "Patients with subsequent infections exhibited significantly elevated levels of fever, PCT, IL-6, and CRP compared to those without infections (P < 0.001)." (PMID 38956649, 2024). "Compared to infection without rAb-ADA, the co-administration of DENV-2 and rAb-ADA resulted in a substantial increase of inflammatory mediator genes IL-1β, IL-6, TNF-α, and CCL2 in Raw264.7 and THP-1 cells." (PMID 37794048, 2023). "Our results indicate that a single dose of IL-6 Tg-PbANKA/LISP2 SPZ, did not fully protect mice against blood stage infection." (PMID 37143657, 2023). "IL-6/STAT3 pathway is involved in a non-specific and acute response of innate immune system to pathogen infection." (PMID 37475019, 2023). "Though IL-6 transgenic SPZ developed into exo-erythrocytic forms in hepatocytes in vitro and in vivo, these parasites were not capable of inducing a blood stage infection in mice." (PMID 37143657, 2023). "We showed that in response to B. pertussis, higher transcript levels of TNF, IL-1β, IL-6 and MIP-2α were detected 6 hours after infection when MPI were cultured without GM-CSF and therefore when STAT5 is inactivated." (PMID 37841236, 2023). "There is an elevation of plasma CRP, interleukin-1 β, interleukin-6, and TNF-α in diabetic individuals without infection." (PMID 37510185, 2023). "In the absence of infection, HTR8/SVneo cells increased IL-6 release when treated with the hydroalcoholic extract (8 μg/mL) or oleoresin (16 μg/mL) in comparison to untreated cells (medium) (*P < 0.01, **P < 0.001) and SDZ + PYR-treated cells (&P < 0.05)." (PMID 36860986, 2023). "Our results also indicated that the addition of nitrite alone decreased IL-6 and IFN-γ but did not change PMN infiltration or histology scores in our rat infection model." (PMID 37800950, 2023). "In AIEC-LF82 infection, the absence of either ELMO1 or NOD2 or both resulted in a significant decline in IL-6 levels compared to C1 cells." (PMID 36694274, 2023). "Our results indicate an increase of Isg15, Ifn-I, Il-6 and Pkr mRNA levels at 6 hours after MVA-Δ3-ISG15AA infection but not in the MVA-Δ3-ISG15GG-infected cells." (PMID 37313341, 2023). "Biomarkers of infection (C-reactive protein (CRP), procalcitonin (PCT), and interleukin 6 (IL 6)) were significantly elevated in NN1 as opposed to NN2." (PMID 36143827, 2022). "While the HIV gag RNA/HIV proteins accumulated in ABs elicited no productive infection in LX2 and immune cells, they triggered ROS and IL6 generation, which, in turn, activated profibrotic genes via the JNK-ERK1/2 and JAK-STAT3 pathways." (PMID 36101437, 2022).
infection (continued). "As expected, infection with ETEC significantly (P < 0.05) increased the levels of TNF-α, IL-6, and IL-8 mRNAs compared to no-treatment control and CP9 alone." (PMID 35736372, 2022). "Our results revealed that IL-10, IL-8, IL-6, IFN-, IL-17A, and IL-17F levels in patients with bacterial lung illness were abnormally higher than those without infection." (PMID 36319826, 2022). "In contrast, moM1 infection with virulent 22653/14 ASFV did not induce the release of either proinflammatory (IL-1α, IL-1β, IL-6, TNF-α) or anti-inflammatory (IL-10) or pro-Th1 (IL-12, IL-18) cytokines." (PMID 35215216, 2022). "The PBS and LacAC4A groups had strong inflammation expression, showing serious infection, while the expression of inflammation in the Cip group was weakened and there was almost no expression of TNF-α and IL-6 in the Cip@LacAC4A group." (PMID 36270992, 2022). "Here we found that increased plasma concentrations of IL-10, MCP-1, IL-1rα, IL-2, IL-6 and SCGFβ had a negative impact on CD4:CD8 ratio during acute infection (< 180 days post infection), as evaluated by linear regression model." (PMID 35165387, 2022). "Our results have shown with the clear of infectious foci, IL-6 returned to the baseline faster than CRP and suggested no recurrent infection." (PMID 36299571, 2022). "Cervical secretions from women with HPV persistence (and therefore cervicovaginal dysbiosis) have upregulated IL-6, TNF-α and immunosuppressive cells compared to women with transient or an absence of infection." (PMID 36303679, 2022). "In line with a reduced ability to produce alternatively activated macrophages, infection-induced levels of RELMα were reduced in the BAL of Ptpn2-LysMCre mice, while IL-4 and IL-13 were not affected and IL-6 and IL-17 were elevated." (PMID 34420044, 2022). "Another limitation to the study is the focus on one type of infection, which is SARS-CoV-2, and the absence of a diversity of IL-6-mediated diseases." (PMID 35626318, 2022). "Fluorescence imaging revealed that neither IL-1β, IL-6, nor LIF significantly modulated the percentage of eGFP+ hiNeurons or hiAstrocytes at 48 h post-infection." (PMID 36680128, 2022). "Third, the latest inflammatory factors, such as IL‐6, IL‐1, tumor necrosis factor alpha (TNF‐α), and the more sensitive infection markers, including procalcitonin, were not included in this study." (PMID 35748095, 2022). "In the absence of any inflammatory insult or IL-6, TGF-β induces Foxp3+ Tregs and suppresses generation of Th17 cells; and on infection or inflammation, IL-6 will suppress the generation of TGF-β-induced Treg cells and induce Th17 mediated response." (PMID 36067164, 2022). "Pro-inflammatory IL-1β, IL-6, and TNF-α cytokines increased in patients bearing hip prosthetics after infection with coagulase-negative staphylococci." (PMID 35203495, 2022). "The level of the inflammatory marker IL-6 was not systematically measured at hospital admission in all the patients and, therefore, we could not evaluate whether it would have an influence on the observed different clinical course of infection between cases and controls." (PMID 35781785, 2022). "In infected RAW264.7 cells, the levels of IL-6 (data not shown) and IFN-γ in the cells infected with RHwx2−/− were significantly higher than those of RH and RHwx2+/+ strains at 48 h post-infection." (PMID 36471417, 2022). "infection may also have a predictive value in terms of the progression of disease and therapy response: patients who are clinical responders to antifungal therapy show a decrease in IL-6 serum levels, whereas non-responders maintain an elevated concentration of the cytokine." (PMID 35741174, 2022). "In contrast, chronic CS exposure (>2 weeks) results in exaggerated cytokine responses (TNF-α, IFN-y, IL-6, IL-12, IL-23, IL-1, IL-5, IL-10, KC, MIP-1a, IL-17, IL-1B) with infection compared to non-smoking infected controls." (PMID 34959590, 2021).